NQO1 (NAD(P)H quinone dehydrogenase 1)
Diseases named in the same sentence as NQO1 in open-access papers (continued):
Sharing a sentence is not in itself a finding about the gene and the disease.
CNS tumor (1 paper, 2025). "The NAD(P)H oxidoreductase 1 (NQO1) enzyme plays a crucial role in protecting cells from oxidative damage but is also involved in the resistance mechanisms of CNS tumors." (PMID 40002465, 2025). "The therapeutic applications of such molecules could potentially complement existing treatments, targeting NQO1’s unique role in CNS tumor resistance to therapy and enhancing treatment efficacy." (PMID 40002465, 2025).
hematologic tumor (1 paper, 2023). "Moreover, due to the high heterogeneity and limited availability of hematological cancer tissue samples within the TCGA database, we could not perform an in-depth exploration to evaluate the impact of NQO1 on all hematologic tumor subtypes." (PMID 37583897, 2023).
immune system disease (1 paper, 2023). "Disease association analysis uncovered the tight correlation of NQO1 and male urogenital disease as well as immune system disease, which showed potential functions in these diseases." (PMID 36846330, 2023).
mitochondrial disease (1 paper, 2018). "Here, we demonstrated that increasing NAD+ through NQO1 represents a promising therapeutic approach for mitochondrial diseases." (PMID 30026729, 2018). "Taken together, our results suggest that pharmacological modulation of NAD+ via the action of KL1333 on NQO1 improves energy balance, decreases oxidative stress, and restores mitochondrial functions and could be used to relieve the deleterious effects of mitochondrial diseases." (PMID 30026729, 2018). "Another NQO1 substrate compound, EPI-743, has been developed as a drug for mitochondrial diseases." (PMID 30026729, 2018).
movement disorder (1 paper, 2012). Neurological conditions resulting in abnormal voluntary or involuntary movement, which may impact the speed, fluency, quality and ease of movement. "In a population with chronic mental illness, various tag SNPs in 7 candidate genes (GRIN2B, GRIN2A, HSPG2, DRD3, DRD4, HTR2C, and NQO1) reached nominally significant (p≤0.05) associations with drug-induced movement disorders." (PMID 23226551, 2012).
vascular disorder (1 paper, 2022). A general term used to describe any disease affecting blood vessels]. "Taken together, these in-vitro and in-vivo investigations, as well as the data reported, show that gene transfer or pharmacological activation of NQO1 in the vascular or circulatory systems may constitute a promising technique for controlling vascular disorders." (PMID 35739970, 2022).
NQO1 also shares sentences with these, for which no sentence is quoted: colorectal tumors (4 papers); heart failure (4); pancreatic ductal adenocarcinoma (4); esophageal adenocarcinoma (3); inflammatory bowel disease (3); Parkinson’s (3); acute leukemia (2); Benign Prostate hyperplasia (2); childhood cancer (2); dysplastic nevi (2); follicular lymphoma (2); fungal infection (2); Glucose intolerance (2); Hearing impairment (2); Huntington disease (2); kidney cancer (2); leukopenia (2); mental disorder (2); myelodysplastic syndrome (2); periodontal disease (2); pneumonitis (2); prostate (2); renal failure (2); schizophrenia (2); skin aging (2); tuberculosis (2); varicocele (2); abdominal aortic aneurysm (1); adrenocortical carcinoma (1); age (1).
A further 110 diseases each share a sentence with NQO1 in 1 paper.